IL13 (interleukin 13)
Diseases named in the same sentence as IL13 in open-access papers (continued):
Sharing a sentence is not in itself a finding about the gene and the disease.
asthma (continued). "It was suggested that the stimulation of HBECs with IL-13 affected the expression of many SARS-CoV-2-related genes and largely inhibited the infection of these cells against SARS-CoV-2, which just explained the relatively low prevalence of asthma in patients diagnosed with COVID-19." (PMID 36524132, 2022). "They identified that IL-13 was predominantly expressed by CD8+ memory T cells, ILC2, and basophils after HDM and LPS challenge, and its expression was largely steroid-resistant in the first two cells, suggesting that IL-13 was a key cytokine driving the pathogenesis of asthma exacerbation." (PMID 36524132, 2022). "We believe this finding is most likely due to the small percentage of IL-13 positivity in phenotype 3, since IL-13 levels in phenotype 3 were found significantly lower even than in phenotype 5 (nonatopic, noneosinophilic severe asthma phenotype)." (PMID 36326393, 2022). "IL-13 knockout mice induced asthma, and the mice did not increase AHR and goblet cell hyperplasia." (PMID 35887041, 2022). "However, while most of the asthma model hallmarks such as AHR did not present significant changes between the NLRP3 deficient mice and the WT, the levels of IL13 and IL33 were slightly but significantly attenuated." (PMID 36189256, 2022). "Moreover, the inflammatory environment of the bronchoalveolar system in patients with asthma could result in a decrease in the expression of the ACE-2, a known SARS-CoV-2 binding receptor, due to IL-13 eosinophil recruitment." (PMID 36523782, 2022). "However, it should be mentioned that under certain conditions, breast milk contains allergens and cytokines (IL-4, IL-5, IL-13, TGF-β, etc.)that might contribute to the development of asthma and airway wall remodeling." (PMID 34834581, 2021). "Additionally, periostin, a marker for asthma responses in the lung, was also decreased following IL-13 neutralization (data not shown), suggesting the neutralization of IL-13 was affecting typical downstream pathways." (PMID 34185704, 2021). "Anti-IL13 treatment has been associated with a greater improvement in Asthma Quality of Life Questionnaire (AQLQ) scores, with a decrease in the use of rescue medication, but has not consistently confirmed an effect on asthma exacerbations." (PMID 33918602, 2021). "In addition, kaempferol treatments attenuated the Th2-driven allergic airway disease in an experimental model of asthma induced by OVA challenge by decreasing the production of IL-5 and IL-13 and ameliorating airway hyperresponsiveness induced by OVA challenge." (PMID 34552650, 2021). "Recent and ongoing trials for asthma may open new possibilities for EGPA treatment: dupilumab is a fully human monoclonal antibody that binds to the alpha subunit of the IL-4 receptor, inhibiting the activity of both IL-13 and IL-4." (PMID 34796188, 2021). "The serum level of periostin is a good indicator for the efficiency of the anti-IL-13 antibody lebrikizumab in the treatment of steroid-resistant asthma but may not be the ideal predictor for the Th2hi phenotype." (PMID 34512647, 2021). "Collectively, anti-IL-13-specific agents are not effective in treating severe asthma." (PMID 35126131, 2021). "Moreover, the same study revealed a significant negative correlation of IL-4, IL-5, and IL-13 (main type-2 cytokines) with ACE2 expression in the airway epithelial cells from participants with asthma." (PMID 34945846, 2021). "The numbers of inflammatory cells and the levels of T2 cytokines (IL-4, IL-5, IL-13, and IL-33) in BALF were increased in the LTE4-alone, OEA-alone, and LTE4-pretreated groups, and these factors play important roles in airway inflammation and asthma remodeling." (PMID 34079051, 2021). "However, the amount of OVA-specific IgE, IL-5, and IL-13 in BALF obtained from macrophage-Arf6 cKO mice decreased compared with that obtained from WT mice, suggesting that macrophages exacerbate asthma-like allergic inflammation through Arf6." (PMID 34423792, 2021).
asthma (continued). "Incidentally, asthma is characterized by increased Th2 cytokine production; however, in this model, Th2 cytokines, including IL-4, IL-5, and IL-13, which were upregulated in the HDM group, were not further upregulated in the HDM/RSV group at the mRNA and protein level." (PMID 34703996, 2021). "In our study asthmatic patients were not included; however, since IL-13 is also crucial for bronchial inflammation in asthma, this finding could help to explain why there is an increased severity of asthma in some Ascaris infected individuals." (PMID 32425942, 2020). "Animal models are useful and can closely mimic clinical features of asthma, mainly airway hyperreactivity (AHR), which relies on T-helper 2 (Th2) cytokine secretion; interleukin (IL)-5 promotes eosinophil recruitment to the lungs, while IL-13 induces goblet cell hyperplasia and mucus production." (PMID 32778730, 2020). "By contrast, serum concentrations reported for IL-13 range from below 1 pg/mL, regardless of whether in healthy probands or symptomatic asthma patients, to between 0.16 and 0.24 ng/mL in diverse populations and patient groups." (PMID 32294982, 2020). "Here, we have analyzed the levels of cytokines such as IL-13, IFN-γ, TNF-α, IL-4, IL-5, and IL-1β and growth factors such as HGF, VEGF, and CSF2 or GM-CSF along with the estimation of serum S1P concentration in asthma patients compared with the healthy controls." (PMID 32637407, 2020). "Early studies in patients with mild asthma have shown that CD4+ T cells favour Th2 type immune responses in BALF, lung tissue, and blood, and secrete large amounts of cytokines, such as IL‐4, IL‐5, IL‐13 and IL‐9, while Th1‐type cytokines such as IFN‐γ, IL‐2 and IL‐12 are reduced." (PMID 33124760, 2020). "In addition to Th17 cells and Treg cells, many immunoregulatory cells, such as Th2 cells, Th1 cells, innate lymphoid cells, dendritic cells, natural killer T cells, and TH9 cells, and many endogenous cytokines related to asthma, such as IL4, IL-5, IL13, IL22, and IL25, are also involved." (PMID 32620122, 2020). "However, findings from STRATOS 2, in terms of effect of tralokinumab on AAER compared with placebo, were not sufficient to support future development of anti–IL-13 therapy with tralokinumab for severe asthma." (PMID 31315668, 2019). "Similarly, the levels of IL-13 and eotaxin were also higher in OVA-induced asthma model than in the normal mice (respectively), whereas DA-treated mice had significantly lower levels than OVA-induced asthma model." (PMID 30991656, 2019). "The eotaxin-3 expression was found optimal from the data set to define type 2 inflammation based on airway mucosal IL-13-driven gene expression and how this related to clinically accessible biomarkers for patients with mild to severe asthma and non-atopic healthy control subjects." (PMID 30778348, 2019). "In view of blocking IL-13 alone is possibly not enough to achieve asthma control because of the overlapping pathophysiological roles of IL-13/IL-4 in inflammatory pathways, combined blocking of IL-13 and IL-4 with monoclonal antibodies may be more encouraging." (PMID 30703143, 2019). "However, there is a lack of evidence regarding the influence of asthma medication, including corticosteroids, on IL-5 and IL-13 production in a co-culture system." (PMID 31861989, 2019). "Since IL-13 uses the type II IL-4 receptor, which is comprised of IL-4Rα (CD124) and IL-13Rα (CD213a), the efficacy of Dupliumab supports the notion that IL-13 may be the more important cytokine in terms of asthma pathology." (PMID 31120919, 2019). "Furthermore, we found no deletions or duplications nominally associated with asthma symptoms in loci consistently associated with the disease in previous studies, including: DENND1B, IL1RL1, PDE4D, TSLP, IL13, HLA-DR/DQ and IL33 regions." (PMID 30262839, 2018).
asthma (continued). "Previous studies have found that IL-13 could contribute to the promotion of goblet cell proliferation, and IL-13 knockout mice with asthma do not exhibit promoted goblet cell hyperplasia in the airways or Muc5AC expression in lung tissue." (PMID 29962952, 2018). "Asthma is an inflammatory disorder characterized by the infiltration of inflammatory cells into lung tissues, hypersecretion of the mucus by goblet cells, airway hypereactivity (AHR), Th2 mediated cytokines and their over-expressions including IL-4, IL-5 and interleukin-13 (IL-13)." (PMID 28694777, 2017). "Yet, in a recently developed mouse model of non-atopic paucigranulocytic asthma, with increased serum IL-13 levels, the role of IL-13 remains largely unknown." (PMID 28704401, 2017). "Furthermore, IL-13-induced periostin and DPP4 can be measured in peripheral blood and are used as biomarkers to predict the efficacy of anti-IL-13 antibodies in human asthma patients." (PMID 28775743, 2017). "It is reported that lebrikizumab, a humanized monoclonal anti-IL-13 antibody that specifically binds to IL-13 and inhibits its function, was associated with improved lung function as measured by FEV1 but did not reduce asthma exacerbations or symptoms as measured by the ACQ5." (PMID 27378934, 2016). "Moreover, we found a much higher secretion of IL-5, IL-13 and IL-25 in the asthma group (P< 0.05), while no significant changes in the anti-IL-25 group were observed (P> 0.05)." (PMID 27617447, 2016). "However, blocking Th2 cytokines such as IL-4, IL-5, and IL-13 despite not been completely explored has shown some promising results in selected patients with asthma." (PMID 26334389, 2016). "Similarly, subcutaneous tralokinumab (formerly CAT-354), an IL-13–neutralizing IgG4 MAb, improves lung function but not global asthma control scores in adults with moderate-to-severe uncontrolled asthma despite controller therapies." (PMID 26334389, 2016). "Thus, it has been questioned whether blocking IL-25 against its receptor IL-17BR could inhibit the expression of IL-13 and IL-5 via nuocytes, and further protect against inflammation in ovalbumin (OVA) induced mouse-model of asthma." (PMID 27617447, 2016). "However, as an important cytokine that promotes asthma, IL-13 failed to exhibit any difference between the two groups." (PMID 27527926, 2016). "Previously, Jung and colleagues found that KWG could inhibit the infiltration of inflammatory cells in ovalbumin (OVA)-induced allergic mouse model of asthma, and decrease OVA-specific IgE and IL-4, IL-5, and IL-13 in the sera and bronchoalveolar lavage fluids." (PMID 27879681, 2016). "Depletion of T cells in sensitized mice inhibits asthma pathology including eosinophil recruitment to the lungs, and the absence of eosinophils decreases IL-4, IL-5 and IL-13 production, and also impairs T cell recruitment/accumulation of effector T cells to the lungs." (PMID 27203689, 2016). "However, this bias was not seen in patients with severe asthma, in whom frequencies of IL-13–secreting TH2 cells were not significantly different from those in healthy subjects, although we did not measure frequencies of IL-4– or IL-5–secreting T cells." (PMID 25746968, 2015). "IL-13 has been shown to mediate features of asthma independent of other cytokines in animal models." (PMID 25848896, 2015). "In sputum neither IL-5 nor IL-13 levels were increased in patients with mild or moderate asthma." (PMID 25746968, 2015). "So far, asthma therapy uses drugs which alleviate the symptoms but do not inhibit the mechanism responsible for the expression of inflammatory mediators such as the cytokines interleukin-4 (IL-4), interleukin-13 (IL-13) and interleukin-5 (IL-5)." (PMID 26117852, 2015). "Because IL-13 is an important cytokine involved in airway remodeling in asthma, IL-33 might augment airway remodeling through its enhancement of IL-13 production from fibrocytes without allergen stimulation." (PMID 24822215, 2014).
asthma (continued). "In addition, we generated conditional knockout mice in which Abl expression in smooth muscle was disrupted, and then evaluated the effects of Abl conditional knockout on airway resistance, smooth muscle mass, cell proliferation, IL-13 and CCL2 in the mouse model of asthma." (PMID 24112389, 2013). "Thus, the asthma loci IL33, IL1RL1/IL18R1, RORA, and IL13 previously identified by GWAS belong to the same pathway, and could modify airway inflammation and interleukin responses that are crucial for the development of asthma." (PMID 23565190, 2013). "Moreover, CCL11 is important in promoting IL-13-associated allergic lung responses since mice deficient in both IL-5 and CCL11 have an intrinsic defect in IL-13 production by T cells and an impaired development of lung eosinophilia and AHR in experimental asthma." (PMID 23936192, 2013). "Besides inhibition of eotaxin-1 and MCP expression by simvastatin, neither IL-13 nor simvastatin treatment changed the expression of other asthma-relevant Th2-type cytokines such as IL-4, CCL5 (RANTES), CCR3, or IL-5Ra." (PMID 22583375, 2012). "In contrast, AMCase was not up-regulated relative to WT mice in the IL-13 (−/−) mouse asthma model." (PMID 21915293, 2011). "IL-13 remains elevated in glucocorticoid (GC) insensitive asthma, but not GC sensitive asthma." (PMID 23283176, 2011). "Other biologic agents targeting IL-5, and IL-4/IL-13 did not demonstrate any serious or severe treatment-related adverse events in asthma patients, There has been some conflicting information on the safety of TNF-alpha blocking agents in the treatment of asthma." (PMID 20016776, 2009). "This supports our hypothesis that increased IL-13 expression in asthma is not reserved to the airway but is also present in peripheral blood inflammatory cells." (PMID 19602238, 2009). "In an animal model of asthma there is increased IL-19 expression and transfer of the IL-19 gene into healthy mice up-regulated IL-4 and IL-5, but not IL-13, however, IL-19 up-regulated IL-13 in “asthmatic” mice." (PMID 18315837, 2008). "This cytokine has not been investigated with respect to CVD but evidence from a study in patients with asthma revealed that women but not men were at increased risk of developing IHD and this could possibly be linked to IL-13." (PMID 18949100, 2008). "Inflammatory cytokines (e.g. IL-13) and mechanical perturbations (e.g. scrape injury) to the epithelium release profibrotic factors such as TGF-β2, which may, in turn, stimulate subepithelial fibrosis in asthma." (PMID 18348727, 2008). "The upregulation of TNF-α and IL-13 suggests that these cytokines may play a key role in mediating this process and highlights the importance of these cytokines as therapeutic targets for RSV induced asthma." (PMID 16893457, 2006). "Similarly, the preventive activities of RosA in female BALB/c mice induced asthma demonstrated that pretreatment with RosA (5–20 mg/kg) 1 h prior to the OVA challenge significantly inhibited increases in Th2 cytokines (IL‐4, IL‐5, and IL‐13) and markedly reduced IgE concentrations in the BALF." (PMID 41523289, 2026). "One possibility for the lack of efficacy of Lebrikizumab in mild asthma patients might be that IL-13 may not be the cytokine responsible for the symptoms in such a patient population, and a role for IL-13 may be significant only in more severe forms of the disease." (PMID 41145900, 2025). "Indeed, two sequential large phase 3 clinical trials did not establish the utility of FeNO in anti-IL-13 biologic therapy; although high FeNO subgroups enjoyed significant reductions in annualized asthma exacerbations in STRATOS1, this finding was not replicated in STRATOS2." (PMID 40863432, 2025).
asthma (continued). "Building on prior research suggesting a role for IL-13 in differentiating asthma from COPD, the primary objective was to determine whether IL-13 levels could distinguish COPD from ACO and discriminate among ACO subtypes, thereby identifying patients who might benefit from IL-13-targeted therapy." (PMID 41002723, 2025). "One possible explanation for this discrepancy might be related to chronic type 2 airway inflammation induced by interleukin (IL)-13 in the airway epithelium, which could elevate ADAM17 expression, leading to the downregulation of ACE2 expression before COVID-19 infection in patients with asthma." (PMID 38241229, 2024). "In addition, histamine is found to promote IL‐10 and inhibit TGF‐α in OVA‐induced asthma in mice, thereby reducing the total number of cells in bronchoalveolar lavage fluid (BALF) and the number of inflammatory factors such as IL‐4, IL‐5, and IL‐13 in lung tissue." (PMID 38687096, 2024). "Our finding of interleukin production as a top PBMC asthma module is not surprising, given the broad representation of this module and the pervasive roles that interleukins play in orchestrating inflammatory processes in asthma, including IL-4, IL-5, and IL-13 in type 2 inflammation." (PMID 37730635, 2023). "Moreover, Cp is found more frequently in asthmatics and the age at which Cp infection occurs seems to be crucial for asthma development as chlamydial infection during early-life (neonatal and infant), but not adult, increases IL-13 expression, mucus-secreting cell numbers and AHR." (PMID 35386652, 2022). "Moreover, the inflammatory environment of the bronchoalveolar system in patients with asthma could result in a decrease in the expression of the angiotensin-converting enzyme 2 (ACE-2), a known SARS-CoV-2 binding receptor, due to interleukin-13 (IL-13) eosinophil recruitment." (PMID 36523782, 2022). "Interestingly, the expression of BIRC3 in GSE76262 was significantly positively correlated with inflammatory cytokines IL-4, IL-5, IL-13, and IL-25 expression (p < 0.05), which implied that BIRC3 may play an important role in the pathogenesis of inflammation in asthma." (PMID 35287655, 2022). "β-HEX’s positive association with IL-5/IL-13 (known promoters of the Th2 response), negative association with IGFBP-1 and IgG2, elevated stability in plasma, and low cost of measurement advocate for the use of β-HEX as a routine biomarker for severe asthma in pediatrics." (PMID 33036262, 2020). "However, in the 1980s, the notion that asthma was nearly always atopic came into prominence, which lead to the use of asthma as an exemplar TH2-mediated atopic disease characterized by TH2 cytokines like IL-4, IL-5 and IL-13, eosinophilia and increased IgE production." (PMID 31120919, 2019). "However, an attenuated IL13 and IL6 response may have particular clinical relevance for respiratory health in endurance athletes, given their central role orchestrating the response to upper respiratory tract infections and implication in asthma." (PMID 31194785, 2019). "Since IL-13 can influence airway inflammation, hyperresponsiveness, fibrosis, and fibroblast functions, these characteristics may have been heightened due to Il13 overexpression in Retnlb−/− mice, thereby suggesting a novel function for RELM-β as a negative regulator of IL-13 in asthma." (PMID 29728628, 2018). "Therefore, biologics targeting IL-4/IL-13 may be useful in patients with proof of T2-high asthma based on the presence of type 2 inflammation regardless of their baseline blood eosinophil levels." (PMID 30050954, 2018). "Consequently, it was reported that IL-4/STAT-6 pathway is involved in asthma pathogenesis because STAT-6 activation lead to the differentiation of naïve T-cells into Th2 effector cells, and it regulates the production of Th2 chemokine induced by IL-4 and IL-13." (PMID 28630596, 2017).